FOXR2 (forkhead box R2)
Synonyms: FOXN6; MGC21658
Tractability: No criterion of Open Targets' tractability assessment is met for any kind of drug.
Gene: Protein-coding gene on chromosome X (55,623,400 to 55,626,192, forward strand). Ensembl gene ENSG00000189299.
Subcellular location: Nucleus
Subcellular location (Human Protein Atlas): Nucleoplasm
Gene Ontology:
Molecular function: protein binding; sequence-specific double-stranded DNA binding; DNA-binding transcription factor activity, RNA polymerase II-specific; DNA-binding transcription factor activity; sequence-specific DNA binding
Biological process: regulation of DNA-templated transcription; regulation of transcription by RNA polymerase II
Cellular component: nucleoplasm; chromatin; nucleus
Homologues: Orthologues: chimpanzee FOXR2 (96% identical), macaque FOXR2 (90% identical), pig FOXR2 (71% identical), dog FOXR2 (68% identical), mouse Foxr2 (53% identical), rat Foxr2 (52% identical), zebrafish foxr1 (31% identical), tropical clawed frog foxr1 (30% identical). Paralogues in human: FOXR1 (53% identical), FOXN1 (18% identical), FOXA2 (15% identical), FOXK2 (15% identical), FOXE3 (14% identical), FOXK1 (14% identical), FOXC1 (14% identical), FOXD4 (14% identical), FOXD4L3 (14% identical), FOXD4L6 (14% identical), FOXD4L5 (14% identical), FOXM1 (14% identical), and 29 more.
Diseases named in the same sentence as FOXR2 in open-access papers:
FOXR2 is named in the same sentence as 51 diseases in open-access papers, as found by Europe PMC text mining. Sharing a sentence is not in itself a finding about the gene and the disease. The quoted sentences say what the papers report.
neuroblastoma (16 papers, 2017 to 2026). Neuroblastoma (NB) is the most common solid, extracranial childhood tumor. "FOXR2 expression can cause and maintain transformation in different types of cells, including CNS and peripheral neuroblastoma cells, as shown by in vitro and in vivo models." (PMID 39866234, 2025). "The fifth case was described in a series of FOXR2-activated neuroblastomas, as a potential diagnostic mimic." (PMID 38500181, 2024). "It is important to note that FOXR2 activity is associated with poor prognosis in neuroblastoma where it was shown to stabilize MYCN protein." (PMID 36337169, 2022). "They found that FOXR2 was highly expressed in various pediatric cancers, including neuroblastoma, DMGs, and sarcomas." (PMID 39866234, 2025). "CNS-NB FOXR2 is a rare form of neuroblastoma, with a peak incidence at the age of five, typically presenting as a mass in the cerebral hemisphere." (PMID 40365336, 2025). "FOXR2 is abnormally expressed in several malignancies, including glioma, neuroblastomas, non-small cell lung cancer, and breast cancer, often correlating with better overall survival." (PMID 39866234, 2025). "CNS-NB-FOXR2 represents a unique subtype of CNS-neuroblastoma characterized by FOXR2 activation and distinct imaging features." (PMID 39866234, 2025). "The function and mechanism of FOXR2 in both CNS and peripheral neuroblastoma need further investigation." (PMID 39866234, 2025). "FOXR2 is essential for these cancers, as shown by FOXR2 knockdown in neuroblastoma cell lines that reduced cell cycle, growth, survival, and MYCN protein levels." (PMID 39866234, 2025). "A case report study revealed that a neuroblastoma tumor with FOXR2 activation had both neuronal and glial differentiation." (PMID 39866234, 2025). "FOXR2 expression is seen in several common malignancies, including neuroblastoma, glioma, sarcoma, and osteosarcoma." (PMID 39866234, 2025). "This confirms that FOXR2 in the ventral telencephalon can produce neuroblastoma-like brain tumors with dual neuronal/glial phenotype and provides a potential explanation to reconcile their glial programs with a likely origin in interneuron lineages." (PMID 39495206, 2025). "Despite the fact that structural variations have been found to activate FOXR2 in some cancers, such as peripheral neuroblastomas and CNS tumors." (PMID 39866234, 2025). "Significance: Profiling the developing brain enabled rationally guided modeling of FOXR2-activated CNS neuroblastoma, providing a strategy to overcome the heterogeneous origins of pediatric brain tumors that hamper tumor modeling and therapy development." (PMID 39495206, 2025). "On the other hand, CNS Neuroblastoma with FOXR2 activation (CNS-NB-FOXR2) is another subgroup within pediatric brain tumors, characterized by alterations in the FOXR2 gene." (PMID 39866234, 2025). "Herein, we report an atypical case of DNA-methylation proven DGONC without a chromosome 14 monosomy and histopathological features resembling a Central Nervous System (CNS) neuroblastoma, FOXR2-activated (CNS, NB-FOXR2)." (PMID 38926880, 2024). "A further overlapping feature with FOXR2-activated neuroblastoma is the gain of chr1q, which was found in two of our cases, and positivity for SOX10 seen in one of two cases tested." (PMID 38500181, 2024). "FOXR2-activated central nervous system (CNS) neuroblastoma (CNS NB-FOXR2) is a recently identified subtype of brain tumor characterized by the elevated expression of the transcription factor FOXR2 mainly due to genomic rearrangements." (PMID 39220247, 2024). "This classifier showed the highest accordance with the methylation class of CNS neuroblastomas with forkhead box R2 (FOXR2) activation (calibrated score 0.98)." (PMID 34468789, 2021). "Furthermore, absence of MYCN amplification in CNS-NB FOXR2 reinforces the crucial role of FOXR2 in neuroblastoma." (PMID 40365336, 2025).
neuroblastoma (continued). "Indeed, pathological features can overlap between embryonal tumor subtypes, particularly those with BRD4::LEUTX fusions and FOXR2-activated neuroblastomas; most notably the small poorly differentiated cells, abundant necrosis, and co-expression of immunomarkers synaptophysin and OLIG2." (PMID 38500181, 2024). "FOXR2 activation is regarded as pathognomonic for CNS neuroblastoma (NB)." (PMID 40237561, 2025). "Frequent (6 of 8) intrachromosomal re-arrangements leading to induction of FOXR2 were also found in neuroblastoma; one tumor without such re-arrangement and FOXR2 induction exhibited focal MYC amplification." (PMID 40075567, 2025). "Subsequent work showed that FOXR2 stabilizes MYCN protein in non-MYCN-amplified neuroblastoma patients, and it presumably also stabilizes non-cMYC-amplified cancers." (PMID 40075567, 2025). "FOXR2 is a pan-cancer oncogene, aberrantly expressed in 70% of adult and pediatric cancer types, including diffuse intrinsic pontine gliomas (DIPG), as well as some extracranial neuroblastoma (EC-NB; 8)." (PMID 39495206, 2025).
medulloblastoma (13 papers, 2017 to 2025). A malignant, invasive embryonal neoplasm arising from the cerebellum. "Medulloblastoma, the most common malignant brain tumor in children, is linked to FOXR2 overexpression, which promotes granule neuron precursor cell proliferation and is associated with the SHH subtype, suggesting FOXR2 as a potential therapeutic target." (PMID 39866234, 2025). "FOXR2 was implicated in the development of CNS-ET such as medulloblastoma." (PMID 39866234, 2025). "Previous large-scale transposon mutagenesis screenings have suggested that FOXR2 is a potential tumor driver gene in medulloblastoma and malignant peripheral nerve sheath tumors." (PMID 39866234, 2025). "A tiny subset of the sonic hedgehog (SHH) subgroup of medulloblastoma, known as FOXR2, is highly expressed." (PMID 39866234, 2025). "FOXR2 is also a gene in medulloblastoma that has undergone the highest insertional mutagenesis using the Sleeping Beauty (SB) transposon." (PMID 39866234, 2025). "FOXR2 is highly expressed in medulloblastoma and also functions as a carcinogen, but the role of FOXR2 in regulating the permeability of glioma conditioned normal BBB has not yet been reported." (PMID 30305135, 2018). "In human medulloblastoma tissues, FOXR2 was overexpressed, and the overexpression of FOXR2 greatly promoted the proliferation of medulloblastoma cells." (PMID 28827892, 2017). "Recently, FoxR2 has been identified as a potential oncogene in malignant peripheral nerve sheath tumors and medulloblastoma through genome-wide functional screens." (PMID 28915588, 2017). "It has been demonstrated that FoxR2 involoved in the tumorgenesis of human solid tumors, such as malignant peripheral nerve sheath tumors, medulloblastoma, breast cancer and human hepatocellular carcinoma." (PMID 28915588, 2017). "FOXR2 is highly expressed in medulloblastoma and acts as a carcinogen." (PMID 30305135, 2018). "Although FOXR2 is a pan-cancer oncogene, the unifying molecular and IHC profiles of NB-FOXR2 tumors suggest a shared lineage of origin, as is the case for other brain tumor types, including hemispheric histone 3 G34R/V gliomas, midline histone 3 K27M gliomas, and subtypes of medulloblastomas." (PMID 39495206, 2025). "The embryonal tumors with FOXR2 overexpression included 11 CNS NB-FOXR2, six pineoblastoma (PB), including five PB-FOXR2 and one pineal anlage tumor (PAT), and one medulloblastoma (MB)." (PMID 40237561, 2025). "Tumor samples and CSF from 25 pediatric EBT patients were analyzed in this study: medulloblastoma (n = 18), ATRT (n = 3), ETMR (n = 1), CNS NB FOXR2 (n = 2) and pediatric EBT NOS (n = 1)." (PMID 37444642, 2023). "Subtyping based on methylation profiling for the PB-MYC/FOXR2 tumors appeared difficult for several cases as in 6 tumors no clearly matching score in the Heidelberg classifier v12.5 were found and in 5 of these cases the highest available score was even for subtype III medulloblastoma (not shown)." (PMID 41291966, 2025).
glioma (11 papers, 2017 to 2025). A benign or malignant brain and spinal cord tumor that arises from glial cells (astrocytes, oligodendrocytes, ependymal cells). "In summary, FOXR2 overexpression, linked to genetic variations and abnormal activation, plays a significant role in the development of pediatric high-grade gliomas and diffuse midline gliomas, contributing to the poor prognosis of these brain tumors." (PMID 39866234, 2025). "FOXR2-associated tumorigenesis involves the overexpression of the FOXR2 gene in various cancers, including gliomas, lymphomas, and prostate cancer." (PMID 39866234, 2025). "Tsai’s team’s research uncovered that FOXR2 is implicated in numerous cancers, including glioma, osteosarcoma, melanoma, and lung cancer." (PMID 39866234, 2025). "Furthermore, glioma patient samples harbored FoxR2 copy number amplification (4%) and missense mutations (1.8%) by analysis of COSMIC online database." (PMID 28915588, 2017). "FOXR2 activation may be a cause of tumor formation, as shown by the presence of L1/FOXR2 fusion transcripts, FOXR2 overexpression, and a tumor methylation profile that matched the original pediatric high-grade glioma that occurred two years before." (PMID 39866234, 2025). "One of the primary factors is the overexpression of FOXR2, which is commonly observed in various cancers, including gliomas, lymphomas, and prostate cancer." (PMID 39866234, 2025). "FOXR2 is a significant target in cancer pharmacology due to its role as an oncogene in various cancers, including gliomas and prostate cancer." (PMID 39866234, 2025). "The present study demonstrated that FOXR2 had high expression in GECs, and silencing of FOXR2 decreased the expressions of ZO-1, occludin, and claudin-5 and increased the permeability of glioma-conditioned normal BBB." (PMID 30305135, 2018). "Then the endogenous expression of FOXR2 was detected and results showed mRNA and protein expression of FOXR2 in glioma-conditioned ECs (GECs) was significantly increased compared with in ECs (P < 0.05)." (PMID 30305135, 2018). "The piR-DQ590027/MIR17HG/miR-153 (miR-377)/FOXR2 pathway plays an important role in regulating glioma conditioned normal BBB permeability and provides a new target for the comprehensive treatment of glioma." (PMID 30305135, 2018). "Our findings, from a view of non-coding RNA regulating the permeability of BBB/BTB, prove that piR-DQ590027/MIR17HG/miR-153(miR-377)/FOXR2 pathway plays an important role in regulating the permeability of glioma-conditioned normal BBB." (PMID 30305135, 2018). "Our study results, from the view of non-coding RNA regulation of BBB permeability, show that the piR-DQ590027/MIR17HG/miR-153 (miR-377)/FOXR2 pathway plays an important role in regulating the permeability of glioma-conditioned normal BBB." (PMID 30305135, 2018). "Our results are correlated with the roles of FoxR2 in glioma cell proliferation, migration and invasion." (PMID 28915588, 2017). "Consistent with previous reports, our data show that the mRNA and protein level of FoxR2 are upregulated in glioma clinical samples." (PMID 28915588, 2017). "Our data suggest that FoxR2 promotes glioma cell proliferation by regulating cell cycle progression." (PMID 28915588, 2017). "In this study, our results demonstrate that FoxR2 contributes to glioma cell proliferation, migration and invasion by regulating the expression of p27 and MMP-2." (PMID 28915588, 2017). "To further examine the effects of FoxR2 on glioma cell proliferation, we used flow cytometry assays to evaluate cell cycle distribution." (PMID 28915588, 2017). "Our study provides insights into the applicability of using the FoxR2 as a potential therapeutic target in gliomas." (PMID 28915588, 2017).
glioma (continued). "Taken together, these data demonstrate that FoxR2 can effectively promote the proliferation of glioma cells." (PMID 28915588, 2017). "We provided evidence that FoxR2 promotes glioma cell proliferation, migration and invasion through regulating the expression of p27 and MMP-2." (PMID 28915588, 2017). "We found that FoxR2 promotes invasion and migration of glioma cells by increasing the expression and activity of MMP-2." (PMID 28915588, 2017). "We found that overexpression of FoxR2 promoted the proliferation, migration and invasion of glioma cells." (PMID 28915588, 2017). "Real-time RT-PCR analysis showed that mRNA levels of FoxR2 were also high expressed in glioma samples." (PMID 28915588, 2017). "In summary, our results show that FoxR2 has critical roles in cell proliferation, migration and invasion of glioma." (PMID 28915588, 2017). "In conclusion, these results suggest that FoxR2 is involved in the migration and invasion function of glioma cells." (PMID 28915588, 2017). "Moreover, downregulation of FOXR2 decreases the transcription and thus the expressions of ZO-1, occludin, and claudin-5, and thereby increases the permeability of glioma-conditioned normal BBB." (PMID 30305135, 2018). "Moreover, down-regulation of FOXR2 inhibited transcription and decreased the expressions of ZO-1, occludin and claudin-5, and further increased the permeability of glioma-conditioned normal BBB." (PMID 30305135, 2018). "Next, we investigated the effects of overexpression FoxR2 on glioma cell proliferation." (PMID 28915588, 2017). "Taken together, these results indicate that upregulation of FoxR2 may confer enhanced tumorigenicity in glioma cells." (PMID 28915588, 2017). "Next, we performed wound healing and transwell invasion assays in FoxR2-overexpressed glioma cells." (PMID 28915588, 2017). "Importantly, overexpression of FoxR2 promotes glioma cell proliferation and invasion through decreasing p27 expression and increasing MMP-2 expression." (PMID 28915588, 2017). "In this study, we investigated the roles of FoxR2 in cell proliferation and invasion of glioma." (PMID 28915588, 2017). "In this study, we investigated the roles of FoxR2 in the tumorigenicity of glioma." (PMID 28915588, 2017). "To determine whether FoxR2 plays an important role in the pathogenesis of glioma, we generated FoxR2 knockout or overexpression glioma cells." (PMID 28915588, 2017). "We examined the protein levels of FoxR2 in five glioma cell lines using Western blot analysis." (PMID 28915588, 2017). "Bioinformatics software prediction (TargetScan) showed binding sites for miR-153 and miR-377 in the 3’UTR of FOXR2 mRNA, indicating that miR-377 and miR-153 may regulate the permeability glioma conditioned normal BBB by adjusting the expression and function of FOXR2." (PMID 30305135, 2018). "However, the effects of FoxR2 on tumorigenicity of human glioma remain unclear." (PMID 28915588, 2017). "Furthermore, we found that FoxR2 could accelerate glioma cell migration and invasion." (PMID 28915588, 2017). "However, the roles of FoxR2 in human glioma development remain unknown." (PMID 28915588, 2017). "However, the functions of FoxR2 in human gliomas remain unclear." (PMID 28915588, 2017). "Silencing of FOXR2 expression significantly decreased the mRNA and protein expression of ZO-1, occludin, and claudin-5, reduced their distribution in the cell membrane, and increased the permeability of glioma-conditioned normal BBB; FOXR2 overexpression had the opposite effects." (PMID 30305135, 2018). "The human glioma tissue specimens apparently had a higher level of FoxR2 expression than non-tumorous tissues." (PMID 28915588, 2017). "In order to investigate the potential roles of FoxR2 in the development of glioma, we first assessed the protein and mRNA levels of FoxR2 in clinical glioma samples and non-tumorous brain tissues by Western blot and real-time RT-PCR, respectively." (PMID 28915588, 2017).
glioma (continued). "Finally, piR-DQ590027 is poorly expressed in glioma-conditioned ECs whereas piR-DQ590027 over-expression could decrease ZO-1, occludin, and claudin-5 expression to further increase glioma-conditioned normal BBB permeability through the piR-DQ590027/MIR17HG/miR-153(miR-377)/FOXR2 pathway." (PMID 31399034, 2019).
pineoblastoma (10 papers, 2021 to 2025). Pineoblastoma is a rare, malignant type of supratentorial primitive neuroectodermal tumor (sPNET), found mainly in children (less than 10% of cases are reported in adults), and located in the pineal region of the brain but that can metastasize along the neuroaxis. "CNS_025, classified as a pineoblastoma MYC/FOXR2‐activated subtype, showed broad 8 chromosomal gain involving the MYC locus, similar to other tumours from this molecular subtype." (PMID 41033792, 2025). "Understanding the role of FOXR2/MYC in pineoblastoma can help in developing targeted therapies aimed at these specific genetic alterations." (PMID 39866234, 2025). "Additionally, Pineoblastoma-FOXR2/MYC and CNS-NB-FOXR2 represent distinct molecular subgroups within the broader category of pediatric brain tumors, each with unique genetic characteristics and implications for treatment and prognosis." (PMID 39866234, 2025). "In the reported German cases, biological relationship to pineoblastoma (PIN MYC/FOXR2) was found." (PMID 38253790, 2024). "Pineoblastoma was is divided into Pineoblastoma, MYC/FOXR2 activated, Pineoblastoma, RB1-altered, Pineoblastoma miRNA-1 and miRNA-2 base on a desirable diagnostic method of DNA methylation profiling." (PMID 38459438, 2024). "In the context of these recent discoveries, the World Health Organization’s 2021 classification for pineoblastoma defined four molecular subtypes: miRNA processing altered 1, miRNA processing altered 2, RB1-altered, and MYC/FOXR2-activated, each with a distinct prognosis." (PMID 37444483, 2023).